FPGT-TNNI3K (FPGT-TNNI3K readthrough)
Gene: Protein-coding gene on chromosome 1 (74,198,235 to 74,544,393, forward strand). Ensembl gene ENSG00000259030.
Genetic constraint (gnomAD): Loss-of-function variants: 139 observed, 116.78 expected, observed/expected ratio (o/e) 1.19, 90% interval 1.04 to 1.37. The upper end of that interval is the gene's LOEUF score, 1.37, which puts it in group 5 of 6, group 1 being the genes least tolerant of losing a copy. Missense variants: 1,196 observed, 1,113.4 expected, observed/expected ratio (o/e) 1.07, 90% interval 1.02 to 1.13. Synonymous variants: 391 observed, 396.64 expected, observed/expected ratio (o/e) 0.99, 90% interval 0.91 to 1.07.